TRAF6 (TNF receptor associated factor 6)
Diseases named in the same sentence as TRAF6 in open-access papers (continued):
Sharing a sentence is not in itself a finding about the gene and the disease.
atherosclerosis (47 papers, 2010 to 2025). A disease characterized by the build-up of fatty material and calcium deposition in the arterial wall resulting in partial or complete occlusion of the arterial lumen. "miR-146a/b-5p can regulate TLR4 downstream moleculesinterleukin-1 receptor-associated kinase 1 (IRAK1) and tumor necrosis factorreceptor-associated factor 6 (TRAF6), thereby resisting atherosclerosis." (PMID 39076378, 2023). "In our hands, Rnd3 deficiency reduced TRAF6 degradation, increased TRAF6 protein levels, and exacerbated endothelial pyroptosis and atherosclerosis by reducing K48‐linked ubiquitination of TRAF6." (PMID 37743632, 2023). "Earlier evidence has denoted that leukocyte deficiency of TRAF6 effectively improved atherosclerosis and restenosis." (PMID 37743632, 2023). "Beyond this MHCII-restricted effect, endothelial TRAF6-deficiency protects from atherosclerosis in female ApoE-deficient mice by inhibiting NF-κB-dependent proinflammatory gene expression and monocyte adhesion to EC." (PMID 35252400, 2022). "Endothelial TRAF6 deficiency reduced atherosclerosis in female ApoE(−/−) mice by inhibiting NF-κB-dependent proinflammatory gene expression and monocyte adhesion to endothelial cells." (PMID 36237831, 2022). "Contrastingly, myeloid cell-specific TRAF6-deficiency caused exacerbated atherosclerosis with larger plaques containing more necrotic areas in both in male and female ApoE-deficient mice." (PMID 35252400, 2022). "TRAF6 is involved in atherosclerosis by inducing inflammatory mediators, and it is associated with excessive inflammation in atherosclerosis-related diseases." (PMID 31766552, 2019). "Endothelial-specific TRAF6 deficiency in females was associated with diminished atherosclerosis and decreased plaque macrophage burden." (PMID 27251057, 2016). "Endothelial TRAF6 deficiency inhibits atherosclerosis by reducing proinflammatory gene expression and monocyte adhesion to endothelial cells." (PMID 23758787, 2013). "This is, however, unlikely since previous reports mainly suggest a pro-inflammatory function of TRAF6 and therefore one would expect reduced levels of atherosclerosis in mice deficient in TRAF6." (PMID 20644648, 2010). "This study investigated the role of TRAF6-deficiency in mice developing atherosclerosis, a chronic inflammatory disease." (PMID 20644648, 2010). "Furthermore, inhibiting the interaction between CD36 and its downstream molecule, TNF receptor-associated factor 6 (TRAF6) almost completely halted the progression of atherosclerosis." (PMID 40284439, 2025). "Based on these data we hypothesized that TRAF6 promotes atherogenesis in mice and associates with atherosclerosis and its complications in humans." (PMID 20644648, 2010). "This evidence emphasizes the TRAF6 as a key driver of endothelial cell activation in atherosclerosis." (PMID 40598260, 2025). "IRAK and TRAF6 are targets of miR‐146a, which mediates the suppressive effect of miR‐146a on innate inflammation in atherosclerosis." (PMID 39392102, 2024). "This study found that IL‐1β enhanced YAP‐mediated chemokine production in macrophages by activating TRAF6, highlighting a pivotal role of TRAF6 in the inflammation‐driven progression of atherosclerosis." (PMID 38778460, 2024). "MiR-146a also targets TRAF6 and inhibits NF-κB activity in ECs, reducing hypoxia-triggered inflammation and atherosclerosis." (PMID 39125620, 2024). "IL18 and TRAF6 nodes in the macrophage autophagy network regulate inflammatory processes and plaque instability in atherosclerosis." (PMID 38984353, 2024). "As expected, Oil Red O staining showed that TRAF6 knockdown mitigated 52.6 ± 3.8% of plaque area formation in ApoeKORnd3ECKO mice, suggesting a signal interaction between Rnd3 and TRAF6 in ECs during atherosclerosis." (PMID 37743632, 2023).
atherosclerosis (continued). "Small-molecule inhibitors that block the interaction between CD40 and TRAF6 (TRAF-STOPs) overcome the current limitations of long-term CD40 inhibition in atherosclerosis, which has the potential to become a future therapeutic for atherosclerosis." (PMID 36237831, 2022). "There it was demonstrated that TRAF6 stop 6877002 treatment in ApoE−/− mice reduces existing atherosclerosis by decreased macrophage activation and leukocyte recruitment." (PMID 36267276, 2022). "Activated CD137 signaling regulates the expression of NFATc1 and its downstream factors in vascular smooth muscle cells through TRAF6/NF-kB p65 pathways, providing a new target for atherosclerosis therapy." (PMID 33791348, 2021). "Activated CD137 signaling also regulates the expression of NFATc1 and its downstream factors in vascular smooth muscle cells through TRAF6/NF-κB p65 pathways, providing a new target for atherosclerosis treatment." (PMID 33791348, 2021). "More importantly, TRAF6-rHDL NPs displayed therapeutic efficacy for treating established atherosclerosis by halting plaque progression and stabilizing the plaque." (PMID 31984429, 2020). "Some scholars have shown that downstream molecules such as MyD88 and TRAF6 also have key effects on atherosclerosis." (PMID 32849545, 2020). "miR-146a has been reported to be involved in the inflammatory process of atherosclerosis, by targeting interleukin-1 receptor-associated kinase 1 (IRAK-1) and TNF receptor-associated factor 6 (TRAF-6)." (PMID 31092195, 2019). "Atherosclerosis involves activation of the IRAK1/TRAF6/NF-κB inflammatory cascade, which is negatively regulated by miR146a." (PMID 29902229, 2018). "There is available literature to demonstrate TRAF6 targeting in cardiomyopathies such as targeted blockage of CD40 and TRAF6 interaction used in the case of atherosclerosis in mouse models." (PMID 30186311, 2018). "On the contrary, a specific TRAF-6 knockout in myeloid cells abrogated atheroprotective IL-10 signaling and exacerbated atherosclerosis." (PMID 28676852, 2017). "CD40:TRAF6 has a critical role in promoting atherosclerosis, as attenuated atherosclerosis and reduced Ly6C+ MC and M1 MØ were observed in CD40−/−TRAF6−/−ApoE−/− but not in CD40−/−TRAF2/3/5−/−ApoE−/− mice." (PMID 28738836, 2017). "Like in atherosclerosis, TRAF6 seems to be the key regulator of CD40 signaling in neointima formation and arterial remodeling." (PMID 27146510, 2016). "Our data challenge the common view of TRAF6 as pro-inflammatory signaling molecule in the context of atherosclerosis." (PMID 20644648, 2010). "Whether remdesivir could ameliorate atherosclerosis through TRAF6 ubiquitination regulated by TAL1 remains unclear." (PMID 40598260, 2025). "TRAF6 deficiency A only attenuated the progression of atherosclerosis without altering the inflammatory response in adipose tissue." (PMID 38995476, 2024). "It was indicated that endothelial cell knockdown of TRAF6 may suppress atherosclerosis itself, in addition to counteracting atherosclerosis aggravated by Rnd3 knockdown." (PMID 37743632, 2023). "In conclusion, miR-146-5p restrains calcification of VSMCs by suppressing TRAF6, which may offer a therapeutical target for atherosclerosis treatment." (PMID 36237831, 2022). "Accumulating studies have demonstrated that TRAF6 participates in atherosclerosis progression." (PMID 36237831, 2022). "We also investigated the mechanisms related to the role of TRAF6, which might offer novel ideas for treating patients with atherosclerosis." (PMID 36237831, 2022). "Therefore, Seijkens and coworkers studied an rHDL NP-mediated approach to suppress atherosclerosis by only targeting the interaction between TRAF6 and CD40 using a small molecule inhibitor (687702)." (PMID 31984429, 2020). "Interestingly, endothelial and myeloid cell TRAF6 proteins have opposite roles in atherosclerosis in ApoE−/− mice." (PMID 23758787, 2013). "In contrast, myeloid cell-specific TRAF6 deletion exacerbates atherosclerosis." (PMID 23758787, 2013).
atherosclerosis (continued). "In summary, we present the novel and surprising finding that TRAF6 deficiency does not influence atherogenesis in mice and does not associate with atherosclerosis in humans." (PMID 20644648, 2010). "Since some pathways (e.g., NF-κB signaling, Notch signaling pathway, and PI3K/Akt signaling pathway) were demonstrated to participate in atherosclerosis development; whether the miR-146-5p/TRAF6 axis can regulate these pathways in Ox-LDL-treated VSMCs should be investigated." (PMID 36237831, 2022). "A role for miR-146a in atherosclerosis is suggested by its ability to negatively regulate several pro-inflammatory factors that promote disease progression, including Toll-like receptor 4 (TLR4), IL-1 receptor-associated kinase 1 (IRAK1), and TNF receptor-associated protein factor 6 (TRAF6)." (PMID 29902229, 2018). "In addition, miR-146a-5p targets TRAF6 and IRAK1, proteins that are part of the CD40 signaling pathway; CD40, which serves an important role in cellular communication during inflammatory responses, is implicated in atherosclerosis." (PMID 26956024, 2016). "Remdesivir impedes atherosclerosis progression by re-establishing the interaction between TAL1 and TRAF6, diminishing endothelial activation." (PMID 40598260, 2025). "Upon stimulation with IL‐1β, a key pro‐inflammatory cytokine involved in atherosclerosis, YAP is K63 ubiquitinated by the E3 ligase TRAF6 at the K252 residue, leading to its protein stabilization and nuclear translocation." (PMID 38778460, 2024). "Targeting TRAF6 MATH is reported to improve insulin sensitivity in obese mice, improve heart function in mouse models of non‐ischemic cardiac failure, reduce atherosclerosis, and inhibit osteoclastogenesis and bone resorption." (PMID 36305766, 2022). "Moreover, miRNA-146a-5p binds to the 3’untranslated region of the TRAF6 gene and inhibit its expression,ultimately reducing vascular TRAF and TLR4 signaling and vascular inflammatoryresponse in atherosclerosis." (PMID 39076378, 2023). "In contrast, our data suggest no role for TRAF6 in the chronic inflammatory disease atherosclerosis." (PMID 20644648, 2010). "In addition, selective TRAF6 inhibition prevents pro-inflammatory cytokine secretion of macrophages as well as immune suppressive side effects by preserving CD40-TRAF2/3/5 (anti-inflammatory) signaling and reducing thereby established atherosclerosis." (PMID 36267276, 2022). "The in vivo study demonstrated that TRAF6-rHDL NPs could reduce the expression of CD40 and integrin in classical monocytes, thereby reducing monocyte recruitment and impeding the initiation of atherosclerosis." (PMID 31984429, 2020). "TRAF6 is located in the cytoplasm and interacts with cell surface receptors like CD40 (a marker of the proinflammatory M1 macrophage phenotype), which is a member of the tumor necrosis factor (TNF) receptor family and plays a role in the progression of atherosclerosis." (PMID 31766552, 2019). "Lack of myeloid TRAF6, but not of endothelial TRAF6, transcriptionally activates NFκB and so leads to increased ER stress and impaired expression of anti-inflammatory cytokines like IL-10 in a mouse model of atherosclerosis." (PMID 31766552, 2019). "Therefore, the down-regulation of miR-146a may increase inflammation-related atherosclerosis and affect vascular damage response by increasing the levels of TNF-α, TRAF6, and IRAK1." (PMID 27164084, 2016). "Finally, aortic atherosclerosis burden and recruitment of leukocytes into the vessel wall were undistinguishable between the two groups, despite higher levels of Irak1 and Traf6 mRNA and protein in the aorta of fat-fed mice lacking hematopoietic miR-146a expression." (PMID 29902229, 2018). "Therefore, overall targeting of TRAF6 may not be a promising treatment strategy for atherosclerosis and probably also other chronic inflammatory diseases." (PMID 20644648, 2010).
atherosclerosis (continued). "It is noteworthy to mention that a selective blocker of the interaction between CD40 and TRAF6 (“TRAF-STOPs”) that does not affect CD40-TRAF2/3/5 interactions and preserves CD40-mediated immunity reduces atherosclerosis, likely by impairing inflammatory leukocyte recruitment." (PMID 35252400, 2022). "Using mice with site-directed mutagenesis for the TRAF6 or TRAF2/3/5 binding site on the CD40 intracellular tail, we demonstrated that CD40-TRAF6 interactions, and not CD40-TRAF2/3/5 interactions, promote the development of atherosclerosis and neointima formation." (PMID 28494768, 2017).
Sepsis (46 papers, 2012 to 2025). Sepsis is defined as life-threatening organ dysfunction caused by a dysregulated host response to infection. "The somatic nuclear autoantigenic sperm protein (sNASP)/tumor necrosis factor receptor-associated factor 6 (TRAF6) axis plays a crucial role in regulating inflammatory responses during sepsis through Toll-like receptor 4 (TLR4) signaling." (PMID 40108019, 2025). "Taken together, it was suggested that TRAF6 signaling is most closely related to ALI caused by sepsis." (PMID 40108019, 2025). "A single nucleotide polymorphism (SNP) in the TRAF6 gene has been linked to an increased vulnerability to acute lung injury caused by sepsis." (PMID 40136419, 2025). "A noteworthy observation is that dampening the activity of tumor necrosis factor (TNF) receptor-associated factor 6 (TRAF6) can alleviate myocardial dysfunction in LPS-induced sepsis." (PMID 37919806, 2023). "Previous research has demonstrated that TRAF6 plays a central role as a mediator in sepsis-associated cardiomyopathy through the Akt signaling, which becomes heightened and exacerbates cardiac injury in LPS-treated mice." (PMID 37919806, 2023). "In sepsis models, it was shown that impaired autoubiquitination of TRAF6 in macrophages leads to an immune-deficient phenotype." (PMID 37261908, 2023). "A microarray analysis was employed to explore sepsis-related changes, and bioinformatics analysis was used to predict lncRNAs binding to tumor necrosis factor receptor-associated factor 6 (TRAF6)." (PMID 37919806, 2023). "Some studies showed that common genetic variants in TRAF6 were significantly associated with susceptibility to sepsis-induced acute lung injury and peripheral blood level of TRAF6 in SAE patients was elevated and related to the severity of SAE." (PMID 36303116, 2022). "Clinically, TRAF6 variant (rs4755453) was significantly associated with susceptibility to sepsis-induced ALI in Chinese Han population." (PMID 35386914, 2022). "TRAF6 is closely related to ALI caused by sepsis, and overexpression of TRAF6 increases the expression levels of TNF-α and IL-6." (PMID 34602057, 2021). "For example, TNF gene SNP rs1800629 is strongly associated with susceptibility to severe sepsis in the Chinese Han population, while genetic variants in TRAF6 are significantly associated with susceptibility to sepsis-induced acute lung injury." (PMID 24901344, 2014). "The association analysis revealed that rs4755453, an intronic SNP of TRAF6, was significantly associated with susceptibility to sepsis-induced ALI." (PMID 22901274, 2012). "Fourteen tag single nucleotide polymorphisms (tagSNPs) in MyD88, IRAK1, IRAK4 and TRAF6 were genotyped in samples of sepsis-induced ALI (n = 272) and sepsis alone patients (n = 276), and tested for association in this case-control collection." (PMID 22901274, 2012). "We reported for the first time that a tag SNP, in the intron region of TRAF6, was associated with sepsis-induced ALI susceptibility in Chinese Han population." (PMID 22901274, 2012). "Our findings indicated that common genetic variants in TRAF6 were significantly associated with susceptibility to sepsis-induced ALI in Chinese Han population." (PMID 22901274, 2012). "Taken together, our findings clearly demonstrated a genetic predisposition that greater TRAF6 mRNA expression might increase susceptibility to sepsis-induced ALI in the presence of clinical risk factors." (PMID 22901274, 2012). "To test this hypothesis, we conducted a case-control study using tag SNP approach to investigate the association of variants in MyD88, IRAK1, IRAK4 and TRAF6 with susceptibility and outcome of sepsis-induced ALI in Chinese Han population." (PMID 22901274, 2012). "Therefore, in this study, we speculated that miR‐126 targeted TRAF6 gene to regulate the NF‐κB signaling pathway, which may be associated with inflammatory response and immune response in sepsis‐induced ALI." (PMID 37248197, 2023).